LINC01905 (long independently transcribed non-coding RNA 1905)
Gene: Long non-coding RNA gene on chromosome 18 (55,892,960 to 56,150,103, forward strand). Ensembl gene ENSG00000267057.
Gene Ontology:
Biological process: RNA processing
Cellular component: nucleolus